CHD4 (chromodomain helicase DNA binding protein 4)
Diseases named in the same sentence as CHD4 in open-access papers (continued):
Sharing a sentence is not in itself a finding about the gene and the disease.
cancer (77 papers, 2013 to 2025). A tumor composed of atypical neoplastic, often pleomorphic cells that invade other tissues. "CHD4 has been associated with the acquisition of a metastatic phenotype in several cancer types, including ovarian, colorectal, papillary thyroid, and breast cancers." (PMID 41417740, 2025). "Conclusively, CHD4-mediated chromatin accessibility is essential for transcriptional reprogramming, which in turn is associated with tumor cell proliferation and cancer development." (PMID 40004553, 2025). "CHD4 is linked to multiple important functions in cancer cells, such as cell cycle regulation, cell differentiation, and DNA repair." (PMID 38594331, 2024). "According to the Cosmic database, we find cancer associated mutations in the KRKR NLS motif (aa 304–307) in human CHD4." (PMID 36861403, 2023). "The upregulated mRNA expression levels of CHD4/7 were significantly associated with high cancer stages in LUAD." (PMID 35467222, 2022). "Our data indicated that LSECtin downregulates the expression of STAT1 through the circFBXL4/miR-146a-5p axis, which ultimately leads to increased expression of FN1/CHD4 resulting in an increased risk of cancer." (PMID 35821222, 2022). "Another study that analyzed spinal schwannomas and paired blood samples using whole-genome sequencing found that CHD4 was in the gene list and had the highest mutation frequency of cancer-related genes." (PMID 36361605, 2022). "Previous studies have indicated that high CHD4 expression was associated with anti-cancer drug and radiation resistance in several different cancer types 25-27, 37-39." (PMID 33994851, 2021). "When BRCA-associated cancer exhibited CHD4 depletion, a DNA-damaging agent (e.g., cisplatin) resistance was observed." (PMID 34142021, 2021). "These mutations showed no impairment of CHD4–DNA interaction or NuRD complex formation, but did show reduced CHD4 protein stability, mimicking a loss of function leading to the up-regulation of the cancer stem cell marker CD133." (PMID 33981601, 2021). "CHD4 has also been implicated in the regulation of transcriptional events involved in oncogenesis and cancer progression through different molecular pathways in several types of cancer." (PMID 33981601, 2021). "A total of 81 point mutations in CHD4 were identified in patients with BC, 19 of which also appeared associated with other cancers." (PMID 33981601, 2021). "In endometrial cancer, CHD4 depletion by specific hot-spot missense mutations promotes tumorigenesis by increasing cancer stem cell characters through the TGFβ signaling pathway." (PMID 34070411, 2021). "Several previous studies have reported the association of CHD4 overexpression with aggressive markers and worse outcome in other cancers." (PMID 33419089, 2021). "Many studies have reported mutations in CHD4 that are related to human diseases, in particular cancer." (PMID 32543371, 2020). "Chromodomain helicase DNA-binding protein 4 (CHD4) is a vital component of the NuRD complex, which is associated with both activation and repression of gene transcription regulating cancer, DNA double-strand break repair, stem cell renewal, and cell cycle." (PMID 31438571, 2019). "In some cancers, CHD4 is mutated with increased frequency, but compelling evidence that these are driver mutations remains lacking." (PMID 31123059, 2019). "While others have shown that CHD4 loss in other cancer contexts causes a delay in DNA damage repair after exposure to DNA damaging agents; it is rarer that its suppression increases γH2Ax expression in the absence of exogenous damage." (PMID 30872624, 2019). "Clinical genome-sequencing projects should be conducted to provide insight into the prevalence of CHD4 mutations in different cancer types and reveal patterns of these mutations." (PMID 32577620, 2019).
cancer (continued). "The loss of CHD4 expression in BRCA-associated cancers, that are sensitive to DNA-damaging agents, such as cisplatin, leads to drug resistance." (PMID 31438571, 2019). "Here, we report a systematic analysis of cancer-derived CHD4 missense mutations on nucleosome remodelling." (PMID 29844320, 2018). "In this study, we have directly assessed the effects of cancer-associated point mutations in CHD4 on nucleosome remodelling activity." (PMID 29844320, 2018). "Taken together, these results suggest regulatory functions for the putative brace and bridge/NegC/Brace-II regions of dMi-2 and CHD4 that are affected by cancer-derived missense mutations." (PMID 29844320, 2018). "The BRD protein ZMYND8 is a component of the NuRD complex that, along with CHD4, displays mutations or altered expression in various cancers." (PMID 27631103, 2016). "Given the evidence for CHD4 function in DNA repair and cell cycle progression, it is perhaps unsurprising that it has also recently been implicated in cancer." (PMID 23697937, 2013). "Therefore, in the current review, we primarily focused on the molecular mechanistic role of CHD4 in different cancers and its association with various cell and immune signaling." (PMID 40004553, 2025). "CHD4 was found to be commonly mutated across various cancer types." (PMID 36362284, 2022). "Our findings describe CHD4, a classically defined repressor, as positive regulator of transcription and super-enhancer accessibility as well as establish this remodeler as an unexpected broad tumor susceptibility and promising drug target for cancer therapy." (PMID 32744500, 2020). "Loss-of-function mutations of CHD4 has been observed in some cancer types." (PMID 32577620, 2019). "Bromodomain Adjacent to Zinc finger domain 1B (BAZ1B), Bromodomain PHD finger Transcription Factor (BPTF), Bromodomain containing 4 (BRD4) and CHD4 are key components of various epigenetic complexes implicated in cancer growth, progression and/or metastasis formation." (PMID 27779108, 2016). "Moreover, CHD4 loss may promote dysregulation in autophagy, which is one of the underlying causes of cancer." (PMID 41278204, 2025). "Here, we speculate that these adjacent mutations in CHD4 and Sth1 both confer a brace conformation that promotes coupling and further support the notion that alteration of coupling may occur more broadly in cancers." (PMID 33058778, 2020). "Interestingly, CHD4 is also implicated as a tumor suppressor in some cancer types." (PMID 32577620, 2019). "Therefore, interpretation of mutations in CHD4 may provide tangible benefit for patients with cancer in the near term." (PMID 32577620, 2019). "Moreover, the cancer sequencing data deposited by the ICGC consortium reveals that Chd4 is mutated in other cancers such as thyroid (27%), ovarian (12%), malignant lymphoma (11%), gastric (10%), skin (10%), bladder (10%) and numerous, cancer-associated, single somatic mutations were identified." (PMID 26075616, 2015). "Here, we show an analysis of Cancer Genome Atlas (TCGA) data using TNMplot, which suggests that CHD4 expression is significantly upregulated in different cancer tissues compared to corresponding normal tissue levels." (PMID 40004553, 2025). "So, it is important that inhibiting CHD4 in cancer cells makes them more sensitive to DNA damage and consequently promote cancer cell death." (PMID 40004553, 2025). "Here, we revisit data that demonstrate the role of CHD4 in cancer progression, tumor cell proliferation, DNA damage responses, and immune modulation." (PMID 40004553, 2025). "A recent report suggested that the depletion of CHD4 sensitizes cancer cells to (PARP) inhibitors in hematopoietic tumors." (PMID 40004553, 2025).
cancer (continued). "Targeting CHD4 might be highly promising, and the screening of more CHD4 inhibitors and mutating of specific targeted sites needs to be further explored through in- vivo and in vitro models that can predict the regulation mechanism, resulting in a promising agent in cancer biology." (PMID 40004553, 2025). "Here, we reviewed studies of an ATP-dependent chromatin remodulator, chromodomain helicase DNA-binding 4 (CHD4), in cancer." (PMID 40004553, 2025). "In OGG1-deficient cells, CHD4 was unable to bind to the tumor suppressor gene promoter, despite 8-oxoGua accumulation, suggesting an upstream role for OGG1 prior to CHD4 in cancer initiation." (PMID 39741341, 2025). "Most of the data published to date related to the involvement of these proteins in cancer immunology focus on CHD4." (PMID 39519018, 2024). "In the present study, we evaluated the prognostic significance of CHD4 expression using in silico analysis of the pan-cancer dataset." (PMID 38594331, 2024). "Similar to other chromatin remodeling factors, genetic and epigenetic data in cancer patients detected frequent alterations in the CHD4 gene suggesting key roles of CHD4 during tumorigenesis and tumor progression." (PMID 38281186, 2024). "It is believed that CHD4, together with its protein partners (e.g., from the NuRD complex), has an oncogenic role in cancer, as it promotes cell growth, migration and invasion, metastasis, and DNA damage repair via silencing various tumor suppressor genes." (PMID 39519018, 2024). "Studies report that CHD4 plays an important role in cancer by participating in histone deacetylation and PPAR-dependent DNA damage repair." (PMID 37894746, 2023). "CHD4 has previously been demonstrated to be required for the metastasis and invasion of cancer cells." (PMID 36681835, 2023). "It is believed that CHD4 mainly plays a role in cancer by participating in histone deacetylation and PARP dependent DNA damage repair." (PMID 36681835, 2023). "Most of the previous studies were focused on the function of CHD4 with tumor cells, cancer stem cells, and cancer cells multidrug resistance." (PMID 35759243, 2022). "A number of studies have indicated the tumor-promoting properties of FN1 and CHD4 in various cancer cells, and these results were consistent with the GC data collected from the TCGA database." (PMID 35821222, 2022). "OGG1 binds to oncosuppressor gene promoters and recruits chromodomain helicase-DNA-binding protein 4 (CHD4), which is associated with cancer." (PMID 36620083, 2022). "Consistently, CHD4, an ATPase subunit of the NuRD complex, was also identified in colorectal cancer as a cancer cell motility regulator." (PMID 36361605, 2022). "Expression of CHD4 can increase stem-cell characteristics in cancer cells, stimulating anticancer drug resistance to DNA-damaging drugs." (PMID 34142021, 2021). "The role of CHD4 in transcriptional gene regulation in both normal and cancer cells has been well documented." (PMID 33981601, 2021). "We investigated the prognostic significance of CHD4 in a large cohort of Middle Eastern PTC patients and explored the functional role of CHD4 in regulating cancer stemness and EMT in PTC cells." (PMID 33419089, 2021). "There are different molecular mechanisms by which CHD4 interacts with different factors to promote cancer development according to the cell context." (PMID 33981601, 2021). "CHD4 has been reported to exert pro-oncogenic activity by promoting tumor progression in several types of cancers." (PMID 33419089, 2021). "PADI1 and PADI3 were co-ordinately regulated in multiple types of cancer cells and their expression was inversely related to that of CHD4." (PMID 33741961, 2021). "The common and cancer type-specific gene transcription regulation should also be further assessed to unveil the detailed function of CHD4 as well." (PMID 34161330, 2021).
cancer (continued). "One of the main reasons for tumor recurrence is the resistance to DNA damage, and genes such as CHD4 enable this repair in cancer cells." (PMID 34142021, 2021). "NuRD or CHD4 is reported to be involved in several important biological functions in cancer cells, such as cell differentiation, cell cycle regulation, and DNA damage repair." (PMID 34161330, 2021). "Depletion of CHD4 is synergistic with DNA methyltransferase inhibition in reducing cancer cell viability." (PMID 33994851, 2021). "It is conceivable that a reduction in overall CHD4 activity in healthy cells contributes to cancer genesis and progression." (PMID 33981601, 2021). "On the contrary, CHD4 knockdown markedly decreased the spheroid growth and stemness markers expressions, verifying the role of CHD4 in maintaining cancer stemness in PTC cells." (PMID 33419089, 2021). "In summary, CHD4 is highly expressed in cancer and is essential not only for FP-RMS tumor cell survival but also for multiple tumor types." (PMID 32744500, 2020). "The results showed that ATM, CHD4, FAT1, KMT2D, MED12, NF2, and SUFU were the most frequently mutated cancer-related genes." (PMID 33193598, 2020). "Several studies have attempted to elucidate the potential mechanisms of CHD4-mediated proliferation on cancer development." (PMID 32228507, 2020). "Strikingly, analysis of genome-wide cancer dependency databases identifies CHD4 as a general cancer vulnerability." (PMID 32744500, 2020). "Mechanistic study reveals that the CHD4/NuRD complex regulates complement gene expression, possibly linking the complement system to cancer progression in HCC." (PMID 32070428, 2020). "Due to its important role in DNA damage repair, CHD4 has been identified as a key determinant in cancer progression, stem cell differentiation, and T cell and B cell development." (PMID 32577620, 2019). "Recently, it has been shown that depletion of CHD4 sensitizes cancer cells to therapeutic agents (e.g. PARP inhibitors and DNMT inhibitors) in both hematopoietic and solid tumors." (PMID 30967373, 2019). "Recent studies have reported that, the depletion of CHD4 sensitizes cancer cells to poly(ADP-ribose) polymerase (PARP) inhibitors and DNMT inhibitors, in both hematopoietic and solid tumors." (PMID 31438571, 2019). "The expression of CHD4 play a dual role in sensitizing cancer cells to chemotherapeutic agents, which provides new insights into the contribution of CHD4 to tumor biology and new therapeutic avenues." (PMID 32577620, 2019). "Recent progress in understanding the role of CHD4 in response to DNA damage suggests the importance of designing effective cancer therapeutic agents that target CHD4." (PMID 32577620, 2019). "Identifying the binding partners of CHD4 and the signaling cascade its involved in will facilitate the generation of models revealing the biological functions of the CHD4 to cancer." (PMID 32577620, 2019). "Despite the increasing characterization of this transcriptional regulator, we still know little about the function of CHD4 in cancer progression as a DNA-repair protein." (PMID 32577620, 2019). "Given the role of CHD4 in the radiotherapy-resistant phenotype, we sought to address the clinical relevance of CHD4 in human cancers." (PMID 31438571, 2019). "For example, the depletion of a chromatin-remodeling factor, such as chromodomain helicase DNA binding protein 4 (CHD4), confers cisplatin resistance in BRCA2-mutated cancer cells." (PMID 31861937, 2019). "While it has been known in other cancers that CHD4 goes to sites of DNA damage, we found CHD4 also regulates expression of RAD51, an essential component of the homologous recombination machinery, which repairs DNA damage." (PMID 30872624, 2019). "Our results help to define the defects of CHD4 in cancer at the mechanistic level and provide the basis for the development of molecular approaches aimed at restoring their activity." (PMID 29844320, 2018).
cancer (continued). "Taken together, our results provide first mechanistic insights into the defects of dMi-2/CHD4 nucleosome remodellers in cancer." (PMID 29844320, 2018). "In contrast, genes in neural (CDS1 and CHD4) and cancer-related (BTG1, COL6A1, PMP22 and HIF1A) pathways were increased by STAT3-KD, and their expression was reduced by STAT3 expression." (PMID 29774125, 2018). "Do different CHD4 mutants create different epigenetic landscapes in cancer cells and if so, would patients then benefit from treatment with different epigenetic drugs?" (PMID 29844320, 2018). "In our system, CHD4 silencing significantly reduces cell proliferation and migration both in vivo and in vitro, suggesting that CHD4 inhibition can be important to block cancer progression." (PMID 27779108, 2016). "Components of several chromatin-remodeling complexes are highly mutated in cancer, including BRG1 and BAF180 in SWI/SNF and CHD4 in NuRD." (PMID 27631103, 2016). "Since Chd4 has ATPase activity, the observed data identify Chd4 as a potentially novel drug target in cancer." (PMID 26075616, 2015). "Genetic alterations in CHD4 are frequently observed in various cancers." (PMID 40004553, 2025). "CHD4 induces PADI1 and PADI3, causing pyruvate kinase isozyme M2 (PKM2) R106 citrullination that enhances serine activation, sustaining glycolysis under hypoxia and reshaping cancer cell proliferation." (PMID 41562091, 2025). "It is now clear that CHD4 expression is upregulated in various cancers." (PMID 40004553, 2025). "Notably, emerging evidence points out that an overexpression of CHD4 and CHD4-mediated suppression of tumor suppression genes is more prominent in several cancers." (PMID 40004553, 2025). "Moreover, CHD4 was also found to regulate extracellular signal-related kinases, which play a dual role (oncogenic/tumor suppressor gene) in cancer." (PMID 40004553, 2025). "Additionally, it has been reported, that CHD4 and NuRD are required for cell growth in different cancer cells." (PMID 38594331, 2024). "Moreover, CHD4 was identified as a new substrate of FBXW7 in the regulation of cancer stemness in TNBC." (PMID 38268032, 2024). "Many cancer types present increased CHD4 levels but variable levels of CHD3." (PMID 39519018, 2024). "Previous reports combined with our results have confirmed that both FBXW7 and Wnt signaling pathways are involved in the stemness regulation of TNBC cells, but it remains unclear whether CHD4 also regulates cancer stem cells in TNBC." (PMID 38268032, 2024). "Interestingly, the regulation of cancer stemness by CHD4 in different malignant tumors is also controversial." (PMID 38268032, 2024). "Along with epigenetic modifiers that were previously implicated in cancer cell fitness, such as CHD1, CHD4, DNMT3B, ELP3, SUPT16H, SUV39H2; novel hits ASH2L, RBX1 and SSRP1 were discovered as essential genes for both U373 and T98G cells suggesting common regulatory role." (PMID 37974198, 2023). "CHD4 has been well documented to be involved in gene repression in cancer cells." (PMID 37372954, 2023). "Nevertheless, emerging evidence points to a role for CHD4 in oncogenic processes, including the epigenetic suppression of tumour suppressor genes, cancer metastasis, cell-cycle transition, cell state determination, chemotherapy tolerance, and epithelial-to-mesenchymal transition." (PMID 36681835, 2023). "Cancer-specific missense mutation A1866D in CHD4 C-terminus domain causes a reduction of CHD4 interaction with ADNP, suggesting that ChAHP formation might be perturbed in cancer cells." (PMID 36945042, 2023). "CHD4 promotes DNA repair from insults such as oxidative damage in cancer cells." (PMID 34142021, 2021). "CHD4 can regulate cancer cell behavior through post-transcriptional modifications." (PMID 34142021, 2021). "To test this idea, we silenced CHD4 in a variety of cancer cell lines." (PMID 33741961, 2021). "Functionally, CHD4 has the potential to promote the growth and migration of several cancers." (PMID 33419089, 2021).